INS (insulin)
Diseases named in the same sentence as INS in open-access papers (continued):
Sharing a sentence is not in itself a finding about the gene and the disease.
diabetes (continued). "Considering that there are approximately 6,000 underweight diabetic patients who are unaware that they have diabetes among the entire Xi’an population of 8 million, these highly likely type 1 diabetes patients may be delayed in receiving lifesaving insulin treatment." (PMID 28874777, 2017). "Growth of the relative area of insulin-positive endocrine cells and Langerhans pancreatic islet perimeter observed in animals with experimental diabetes mellitus receiving ZB-16 at a dose of 1 mg/kg support the hypothesis that it acts as a protective agent for β-cells." (PMID 28736546, 2017). "In addition, these results were confirmed by recent data demonstrating that in situ (in pancreas sections from diabetes autoantibody-positive donors), insulin area and beta cell mass can be maintained prior to disease onset and that production of proinsulin increases." (PMID 28770323, 2017). "Therefore, to further and deepen the research on MBBP, the experiment in this study mainly focuses on the oral administration of MBBP for treating diabetes and on investigating its possible mechanisms of action related to glucose metabolism and insulin secretion." (PMID 28970780, 2017). "The biological reasons why insulin may provide a slightly stronger protective effect is unclear, but may be due to the role of T2D severity in protection from fibroids, as women who are on insulin may have more severe forms of diabetes." (PMID 28399866, 2017). "This study of percutaneous coronary revascularization in patients with a prior history of diabetes and cardiovascular risk factor control reveals increased mortality only in patients with diabetes mellitus requiring insulin treatment but not in those on diet control or oral hypoglycemic agents." (PMID 28029209, 2017). "In guinea pigs, pro-inflammatory cytokines such as tumor necrosis factor (TNF)-alpha and interleukin 6 (IL-6) produced during inflammation promote the release of free fatty acids from adipose tissue which may reduce insulin action on skeletal muscles resulting in dysglycaemia and diabetes mellitus." (PMID 28137307, 2017). "Ideally, intelligent CGM devices could be linked to an insulin delivery pump to form an artificial pancreas, and the benefit of CGM point-of-care tests for the self-management of diabetes patients is the reduced time length spent in hypoglycemia and the increased time in euglycemia." (PMID 28106820, 2017). "Diabetes mellitus has been classified in two types: Type 1 diabetes (T1D)—an autoimmune disorder that provoke the destruction of pancreatic β-cells and Type 2 diabetes (T2D)—an alteration in glucose regulation due to a combination of dysfunctional pancreatic β cells and insulin resistance." (PMID 28587101, 2017). "Diabetes mellitus was not defined as a part of PC1/3 deficiency although it can be speculated that there must be a relative insulin deficiency due to the defect in conversion of proinsulin to insulin." (PMID 28588004, 2017). "Diabetes mellitus (DM) is a chronic metabolic disease in which the body cannot produce enough insulin or effectively utilize it." (PMID 28583071, 2017). "While genetic catalase deficiency is associated with diabetes in humans and animals, our data suggests that in the general population, catalase activity is increased, rather than deficient, in adipose tissue of insulin resistant subjects." (PMID 28545081, 2017). "A combination of the reported data demonstrates that NGF could be used inpatients with type 2 diabetes mellitus because of its ability to maintainβ-cell function, stimulate insulin secretion, and simultaneously impedethe development of diabetes mellitus and its comorbidities." (PMID 28740732, 2017). "Therefore, abnormality of the insulin pathway in insulin target cells could be critical for the pathogenesis of diabetes." (PMID 29209160, 2017).
diabetes (continued). "Although they measured the serum insulin level which is known to be secreted into the blood stream in equimolar ratio with C-peptide, the amount of viable β-cell mass available at the point of diagnosis is a determinant for the type and/or phase (early or late) of diabetes under investigation." (PMID 28129400, 2017). "Importantly, as early as 14 days after birth, mutant mice showed defects in insulin production, beta cell growth and survival before the onset of diabetes, indicating that mTORC1 directly regulates these functional characteristics, eventually leading to a loss of functional beta cell mass." (PMID 28598424, 2017). "They had hypertension, dyslipidemia, fatty liver disease, and poorly controlled diabetes (glycated hemoglobin 8.3% and 10.2%, respectively) despite the use of three classes of oral antidiabetic drugs taken in combination in the first case, and high doses of insulin in the second case." (PMID 28086952, 2017). "Furthermore, although defective glucose‐stimulated insulin production by dietary Se deprivation exacerbates glucose intolerance and diabetes in the mice, such a condition may oppositely promotes longevity through reduced metabolism." (PMID 27653523, 2017). "Reduced insulin sensitivity with continuous hepatic production and a release of glucose in the fed state is thought to result in long-term hyperglycemia and hyperinsulinemia and to impair muscle insulin sensitivity, and thereby promoting the development of type 2 diabetes mellitus." (PMID 28926951, 2017). "Hyperthyroidism provocated from toxic nodular goiter is responsible for increased insulin degradation, increased glucagon secretion, and increased hepatic glucose production, all these factors which aggravate insulin resistance and glyceamic control of the patients with diabetes." (PMID 29214182, 2017). "In the field of diabetes, some games for education of patients and a few technology-based initiatives for education of health professionals have been described, but to our knowledge, no game has been previously reported for education of health professionals on diabetes or insulin." (PMID 28279950, 2017). "Post-hoc analysis of the Diabetes Prevention Trial-Type 1 (DPT-1), where at risk children were fed high doses of insulin, also indicated that it may be necessary to select individuals with high IAA levels for antigen-specific trials with insulin." (PMID 29387056, 2017). "However, OPN, which is attracting attention for its involvement with diabetes and obesity in multiple organs, is surmised to play a major role in the pancreas under hyperglycemia and high-insulin conditions as well, and it is believed that the action mechanism requires clarification." (PMID 28417915, 2017). "Diabetes education, be it individual or in groups, needs to consider local contexts such as patients’ religious backgrounds and their socio-economic contexts in addressing about the use of holy water, medication adverse effects and insulin storage among other things." (PMID 28405339, 2017). "We have confirmed in our group of normoglycemic women with no family history of diabetes that plasma leptin levels were positively associated with BMI and negatively with insulin sensitivity indexes, whereas the opposite was found both for adiponectin and HMWA." (PMID 28626772, 2017). "In Diabetes Mellitus (DM), normal physiological processes do not occur and chronic hyperglycaemia is apparent, where glycaemic control is severely impaired as a result of a deficiency in insulin or its action." (PMID 28779138, 2017). "Furthermore, MODY3 is defined as a non-ketotic and autosomal dominantly inherited form of diabetes characterized by a severe deficiency in insulin secretion." (PMID 28410371, 2017).
diabetes (continued). "With such large injectable doses of synthetic insulins remaining in the physiological system for extended periods of time, in some case 24–40 hours, double and triple dose insulins may impact adversely on personalised insulin profiling in patients with diabetes." (PMID 28779138, 2017). "For example, metformin may have been used in less severe cases of diabetes compared to insulin." (PMID 28708856, 2017). "Finally, we lacked data on specific characteristic of T2DM such as glycosylated hemoglobin measurements, blood glucose levels, use of insulin or antidiabetic drugs or duration of the disease, therefore we cannot assess the effect of diabetes control on our outcome variables." (PMID 28837689, 2017). "The model predicted that some doses of insulin are able to stimulate the fast glucose uptake and its accumulation as fat in hypertrophic adipocytes that may trigger the circadian cycle, leading to relapse of diabetes." (PMID 28884000, 2017). "Since, there is no insulin deficiency, at least in the early stage of diabetes, it is obvious that pancreatic β cells are not at fault; but this implies that islet cells are not able to secrete enough insulin to overcome peripheral insulin resistance in these patients." (PMID 28824543, 2017). "In addition, male sex, higher BMI, diabetes, higher HbA1c, insulin use, hypertension, ACEI or ARB use, dyslipidemia, statin use, higher NYHA, β-blocker use, and a history of cerebrovascular disease were associated with an increased number of infarcted coronary arteries." (PMID 26676906, 2016). "At 40 weeks old, the insulin spike may not have caused clinically-evident diabetes in the mice, but the disease may have become more pronounced if the mice aged further." (PMID 27095067, 2016). "Lack of blood glucose-lowering insulin after malfunction or autoimmune destruction of the pancreatic β-cells is the recognized cause of diabetes, but recent evidence indicates that diabetic hyperglycaemia would not develop unless lack of insulin was accompanied by hypersecretion of glucagon." (PMID 27044660, 2016). "In diabetes, some insulin signaling pathways may be disrupted." (PMID 27579151, 2016). "Lack of a specific antibody response in the NOD mice is not a consequence of deficient B-cell function, since during the diabetes development these mice develop high titers of autoantibodies to a large number of self-antigens including Glutamic Acid Decarboxylase of 65 KDa (GAD65) and Insulin." (PMID 28074170, 2016). "Interestingly, even with higher values of serum insulin, adults develop diabetes." (PMID 26985241, 2016). "Vanadium might be a valuable supplement to insulin in the treatment of diabetes mellitus." (PMID 26459400, 2016). "We updated our previously published systematic reviews for type 1 diabetes mellitus comparing long- and intermediate-acting insulin regimens (from January 2013 to June 2015) and for Alzheimer’s dementia comparing cognitive enhancers (from January 2015 to May 2015)." (PMID 26975720, 2016). "In future studies, THS exposure could be a reproducible and quantifiable model to determine how tobacco toxins can cause alterations to insulin signaling and sensitivity which can lead to diabetes in non-obese individuals." (PMID 26934053, 2016). "CaMKII activity is tightly correlated with diabetes symptoms, and inhibition of the enzyme complex reportedly produces an impaired glucose tolerance; β cells store Ca2+ in mitochondria and the ER, and damage to either organelle can greatly alter both Ca2+ levels and insulin release." (PMID 27092078, 2016). "Therefore, pharmacological activators of Sirt6 may be a promising therapeutic tool for promoting insulin secretion in patients with diabetes." (PMID 27457971, 2016). "Diabetes mellitus (DM) is a kind of metabolic diseases characterized by chronic hyperglycemia due to either reduced insulin secretion (type 1 DM) or insulin resistance (type 2 DM)." (PMID 27067643, 2016).
diabetes (continued). "The goal of the current study was to investigate whether phlorizin has beneficial effects on obesity and its complications, including diabetes and inflammation, by suppressing fat accumulation and regulating plasma glucose, insulin, and adipokine levels in C57BL/6J mice." (PMID 26891322, 2016). "In this form of diabetes, the glycemic control may be labile due to the loss of not only the insulin production, but particularly due to the loss of glucagon secretion." (PMID 27605208, 2016). "Diabetes mellitus (DM) is a common metabolic disease characterized by hyperglycemia due to insulin resistance or impaired insulin secretion." (PMID 27808173, 2016). "Thus, deficiency of insulin rather than insulin resistance was the hallmark of this animal model developed to study metabolic syndrome in the setting of diabetes mellitus." (PMID 26880906, 2016). "However, one of the most common malfunctions of β-cells is caused by lack of insulin, leading to the development of diabetes." (PMID 27881904, 2016). "In a similar experiment, both intrathecal insulin and IGF1 were able to reverse the loss of epidermal nerve fiber density and length in diabetic rats, which is a well-documented and quantifiable consequence of the “dying back” neuropathy associated with diabetes." (PMID 28066166, 2016). "Interestingly, in addition to cardioprotective effects related to its antioxidant and anti-hypertrophic properties, RES could improve insulin sensitivity in animal models of diabetes and metabolic syndrome, in relation to anti-diabetic effects." (PMID 27144581, 2016). "However, in the case of type 1 diabetes mellitus, which is insulin-depleted, a regimen that involves initiation of insulin administration at very low dose, before increasing the dose, is difficult, because of risks of severe hyperglycemia and diabetic ketoacidosis." (PMID 26838553, 2016). "As it was demonstrated that metformin, the first-line medication for the treatment of type 2 diabetes, could inhibit TDO2, a key enzyme in tryptophan metabolism, we assessed the potential impact of diabetes therapy (except insulin, as patients on insulin therapy were excluded) on KPm concentrations." (PMID 27327770, 2016). "Type 2 diabetes mellitus (T2DM), which is a complex metabolic disease that results from peripheral insulin resistance and reduced insulin secretion, comprises about 90% of the global cases of diabetes mellitus (DM)." (PMID 27111895, 2016). "A larger body of evidence has suggested that regular consumption of nuts, such as pistachios, as part of a moderate-fat diet, could have important glucose- and insulin-lowering effects, promote a healthier metabolic profile, and reverse certain metabolic consequences of pre-diabetes." (PMID 26944400, 2016). "The genetic profile of the CDr rats protected them and enabled the maintenance of adequate glucose-stimulated insulin secretion (GSIS), despite the low-level of copper in the HSD diet, while the genetic diabetic sensitive rat—CDs—were susceptible to the HSD diet that initiated Type-2-like diabetes." (PMID 27458721, 2016). "Furthermore, for drugs which are usually prescribed in long-standing diabetes, such as insulin, the inclusion of subjects with diabetes micro- and macrovascular complications, especially retinopathy and neuropathy, should be taken into account when evaluating fracture risk." (PMID 28044077, 2016). "A recent cross-sectional clinical study of serum sFRP4 in humans with type 2 diabetes mellitus compared to pre-diabetes and normal glucose tolerance subjects revealed higher sFRP4 in subjects with diabetes and a positive correlation between sFPR4 and age, insulin levels, HbA1c and triglycerides." (PMID 27685706, 2016).
diabetes (continued). "Indeed, because STZ causes an incomplete β-cell ablation due to variations in administration protocols and in genetic background-dependent sensitivity, it is possible that the “diabetes resistance” phenotype of Gcgr-/- mice relies on the action of insulin from residual β-cells." (PMID 27092792, 2016). "Diabetes mellitus (DM) is a chronic disease characterized by hyperglycemia resulting from deficits of insulin secretion, insulin action, or both." (PMID 27812609, 2016). "Altogether, chronically high insulin or glucose levels in the lungs may promote airway hyperresponsiveness and airway remodelling and thereby contribute to reduced lung function or incident asthma in patients with diabetes." (PMID 27212806, 2016). "Similarly, our findings revealed that diabetes led to remarkable decrease in serum insulin levels." (PMID 27602318, 2016). "Diabetes mellitus type 1 is caused due to lack of insulin secretion." (PMID 26885249, 2016). "Also frailty in some patients with diabetes is associated with weaker muscle strength rather than less muscle mass which is responsible for less insulin sensitivity." (PMID 28031949, 2016). "For those patients with a wash-in of at least 365 days to diabetes presentation from the later of their registration date and practice up-to-standard date, 410 and 145 deaths were observed for those treated with insulin monotherapy and insulin plus metformin, respectively." (PMID 27152598, 2016). "Metformin is the most commonly used OHA among diabetes patients and its mechanisms are to reduce hepatic glucose output and increase insulin mediated utilization of glucose in the periphery, to restore insulin signalling pathways, and to improve insulin sensitivity in peripheral tissues." (PMID 27195294, 2016). "Diabetes mellitus (DM) is a metabolic disorder that occurs as a result of inability of the body to secrete insulin, or to make use of the insulin produced, or both." (PMID 27004114, 2016). "Insulin and insulin-like growth factor-1 (IGF-1) signaling, by IGF-1R, are differentially involved in keratinocyte differentiation, promoting the inhibition of normal keratinocyte differentiation, suggesting that abnormal insulin signaling, as what occurs in diabetes, may lead to skin pathology." (PMID 27840833, 2016). "Type 2 diabetes mellitus (T2DM), is a heterogeneous disorder characterized by multiple defects in insulin action in tissues (muscle, adipose, and liver) and defects in pancreatic insulin secretion; this eventually leads to loss of pancreatic insulin-secreting cells." (PMID 26930607, 2016). "Type 2 diabetes mellitus (T2DM) is the most common type of DM, in which insulin resistance develops and leads to a decreased response of the peripheral tissues to insulin activity." (PMID 27187435, 2016). "This approach could therefore be used to target numerous receptors, such as insulin, neuronal nicotinic acetyl choline, vascular endothelial growth factor receptors, etc., for the treatment of diseases, like diabetes, Alzheimer’s disease, schizophrenia and tumors." (PMID 27231900, 2016). "Therefore, they are associated with pathogenesis of insulin resistance via the inhibition of insulin signals and dysregulation of adipocytokines/adipokines which play an important role in the progression of diabetes, hypertension, atherosclerosis, and even cancer." (PMID 26880905, 2016). "Furthermore, the absence of an association between overall or site-specific cancer risk and increasing duration of diabetes in our study does not support a dose–response relationship between exogenous insulin use and cancer incidence." (PMID 26924393, 2016). "However, as well reviewed by Wolfsdorf in one of the last issues of Pediatric Diabetes, controversy persists concerning the appropriate starting dose of insulin for the treatment of DKA and the optimal fluid treatment regimen for pediatric DKA, also at an international level." (PMID 26649321, 2016).